CXCL11 (C-X-C motif chemokine ligand 11)
Diseases named in the same sentence as CXCL11 in open-access papers (continued):
Sharing a sentence is not in itself a finding about the gene and the disease.
metastatic melanoma (3 papers, 2016 to 2024). A melanoma that has spread from its primary site to another anatomic site. "Pretreatment serum levels of CXCL11 have been linked to poor overall survival in patients with metastatic melanoma treated with anti-CTLA-4 ICI therapy." (PMID 39736644, 2024).
multiple myeloma (3 papers, 2017 to 2024). "The expression of CXCL11 in myeloma cells was detected by qRT-PCR, U266 and RPMI 8226 cells were chosen for the subsequent experiment.We then stably suppressed CXCL11 in the two cell lines by lentiviral transfection." (PMID 35568859, 2022).
nasopharyngeal carcinoma (3 papers, 2020 to 2026). A carcinoma arising from the nasopharyngeal epithelium. "Based on these references CXCL9, CXCL10 and CXCL11 are likely to influence tumorigenesis from inflammation-related nasopharyngeal cancer." (PMID 32986378, 2020).
renal carcinoma (3 papers, 2014 to 2022). A carcinoma arising from the epithelium of the renal parenchyma or the renal pelvis. "SN12C and A498 cells migrated toward CXCL12 and CXCL11; the migration toward CXCL12 was inhibited by anti-CXCR4 and Peptide R, whereas CXCL11-induced migration was inhibited by anti-CXCR7 demonstrating that both chemokine receptors affected migration in renal cancer cells." (PMID 24991762, 2014).
SARS-CoV infection (3 papers, 2014 to 2020). "The T cell chemoattractant, CXCL11 was elevated in both age groups with SARS-CoV infection." (PMID 24642138, 2014).
Sjögren syndrome (3 papers, 2018 to 2024). "CXCL9 protein levels (along with CXCL10 and CXCL11) were elevated in tears and conjunctival epithelium from Sjögren syndrome patients compared to controls samples." (PMID 30347820, 2018). "This study aimed to investigate the serum and expression levels of C-X-C motif chemokine ligand 9 (CXCL9), CXCL10, CXCL11, and CXC receptor 3 (CXCR3) in minor salivary glands (MSGs) of patients with primary Sjögren’s syndrome (pSS), and to explore their correlations with clinical parameters." (PMID 38900301, 2024).
Stroke (3 papers, 2022 to 2023). Sudden impairment of blood flow to a part of the brain due to occlusion or rupture of an artery to the brain. "Immunostaining demonstrated the expression of CXCL10 protein, but not CXCL9 or CXCL11, along CD31+ vessels in the ischemic brain 1 day after stroke." (PMID 35912857, 2022).
T cell lymphoma (3 papers, 2019 to 2025). "CXCL11 is positively correlated with tumor-infiltrating CD8+ T cells in mice subjected to a transgenic administered with CXCL11-EL4 t-cell lymphoma cells." (PMID 37547756, 2023). "It has been reported that mice challenged with EL4 T-cell lymphoma cells genetically modified to produce murine CXCL11 attracted more CD8+ lymphocytes and macrophages with anti-tumoral activity to the TME compared to WT EL4 T-cell lymphoma cells." (PMID 31216755, 2019). "A positive correlation was observed between CXCL11 and tumor-infiltrating CD8+ T cells in mice subjected to genetically modified CXCL11-EL4 T cell lymphoma cells." (PMID 40651961, 2025).
ulcerative colitis (3 papers, 2022 to 2025). An inflammatory bowel disease involving the mucosal surface of the large intestine and rectum. "Evidence from inflammatory and clinical cohorts indicates that Family_XIII_AD3011_group is associated with inflammatory markers or pathways in ulcerative colitis and psychiatric contexts, and Mendelian randomization further links this genus to CXCL11-mediated inflammatory signaling (59, –, 61)." (PMID 40985686, 2025). "The expression of the three ligands of CXCR3 (CXCL9, CXCL10, and CXCL11) is significantly increased in various diseases such as interstitial cystitis, ulcerative colitis, and myositis, and previous studies found that blocking CXCL10 can reduce the degree of the damage of these diseases." (PMID 35036436, 2022). "A negative correlation between CXCL11 and galectin-3 has previously been found in serum from individuals with ulcerative colitis." (PMID 39044165, 2024).
acne (2 papers, 2014 to 2024). An inflammatory process of the sebaceous glands which is characterized by comedones, nodules, papules and/or pustules on the skin. "Similar results were observed in a cohort study, the CXCR3 ligands CXCL9, CXCL10, and CXCL11 were overexpressed in acne lesions." (PMID 38321132, 2024). "Similar findings were observed in the German cohort, since STAT1 a positive regulator of Th1 development was induced, and the CXCR3 ligands CXCL9, CXCL10 and CXCL11, were overexpressed in lesional acne skin." (PMID 25153527, 2014).
acute respiratory distress syndrome (2 papers, 2023). Progressive and life-threatening pulmonary distress in the absence of an underlying pulmonary condition, usually following major trauma or surgery. "For example, CXCR3, the receptor for CXCL10 and CXCL11, is commonly associated with expression on T cells and lymphocytes but has been shown to be expressed on lung neutrophils from patients with acute respiratory distress syndrome." (PMID 37809107, 2023).
astrocytoma (2 papers, 2020 to 2024). "In addition, CXCL11 and CXCL12 were low or absent in the astrocytoma and in the M2 macrophage secretome." (PMID 38472446, 2024).
atrophic gastritis (2 papers, 2010 to 2025). "NichNet analysis revealed that a subpopulation of CXCL11+APOE+ fibroblasts regulated the inflammatory response in the pathogenesis of atrophic gastritis." (PMID 39905493, 2025).
basal cell carcinoma (2 papers, 2021 to 2023). A carcinoma involving the basal cells. "However, taste transduction, basal cell carcinoma, and hedgehog signaling pathways were enriched in the CXCL11‐negative group." (PMID 34047476, 2021).
Chlamydia infection (2 papers, 2021). "Chlamydia infection also induced a significant mRNA upregulation of the chemokines CXCL10, CXCL11, CCL20, and RANTES." (PMID 34684219, 2021). "Next, we explored whether the expression of IFN-γ and IFN-γ induced genes was altered in FP- and BUD-treated lung tissues, including the typical, inducible defence genes against Chlamydia infection, such as indoleamine 2,3-dioxygenase 1 (IDO1), IDO2, MIG/CXCL9, IP-10/CXCL10 and I-TAC/CXCL11." (PMID 33799333, 2021).
Cognitive impairment (2 papers, 2021 to 2025). Abnormal cognition is characterized by deficits in thinking, reasoning, or remembering. "Two studies reported significantly different concentrations of markers in individuals with MCI: CXCL11, CCL13, and CCL15 were increased, and CXCL16 and IL-16 were decreased in individuals with mild cognitive impairment compared to controls." (PMID 40711681, 2025).
colonic diseases (2 papers, 2025). "Summarizing these results, we identified 5 proteins (CCL20, CXCL1, CXCL11, HGF, and IL-24) with increased abundance in colonic diseases, irrespective of the disease entity (colonic CD and UC) that significantly correlated with both, tissue gene expression and inflammatory severity." (PMID 40291692, 2025).
coronary artery disease (2 papers, 2018 to 2021). "Following heart transplantation, elevated CXCL11 levels have shown an association with the development of severe transplant coronary artery disease." (PMID 30210493, 2018). "Pro-inflammatory chemokines CXCL11 was increased in patients with severe transplant coronary artery disease." (PMID 34987524, 2021). "CXCL10 is the most extensively studied of the three chemokines in the clinical setting of ischemic heart disease; less is known about the role of CXCL9 and CXCL11." (PMID 30210493, 2018).
cystitis (2 papers, 2008 to 2018). Inflammation of the urinary bladder. "CXCL11 mRNA expression in male urothelium with intermediate (48 h) CYP-induced cystitis was significantly (p ≤ 0.01) greater than expression with chronic CYP treatment." (PMID 29681802, 2018). "Intermediate (48 h) CYP-induced cystitis significantly (p ≤ 0.01) decreased CXCL11 transcript expression in detrusor of female mice." (PMID 29681802, 2018). "Intermediate (48 h) CYP-induced cystitis significantly (p ≤ 0.01) increased CXCL11 transcript expression in detrusor of male mice whereas 4 h and chronic CYP-induced cystitis significantly (p ≤ 0.01) reduced CXCL11 mRNA transcript expression." (PMID 29681802, 2018). "CXCL11 mRNA expression in male urothelium with acute (4 h) cystitis was significantly (p ≤ 0.01) greater than expression with 48 h or chronic CYP treatment." (PMID 29681802, 2018). "In contrast, CXC mRNA transcript expression changes in male mice with cystitis were primarily decreases in expression (CXCL9-11) in the urothelium but both increases (CXCL10) and decreases (CXCL9, CXCL11) in expression were observed in the detrusor." (PMID 29681802, 2018). "The CXC chemokine family is pro-inflammatory with family members CXCL9, CXCL10, CXCL11, and their common receptor, CXCR3, contributing to urinary bladder inflammation." (PMID 29681802, 2018). "In contrast, CXCL11 protein expression in the whole urinary bladder of female mice significantly (p ≤ 0.01) decreased with intermediate (48 h) and chronic CYP-induced cystitis." (PMID 29681802, 2018). "CXCL11 mRNA expression in male detrusor with intermediate (48 h) cystitis was significantly (p ≤ 0.01) greater than that following acute (4 h) and chronic CYP-induced cystitis." (PMID 29681802, 2018). "CYP-induced cystitis in mice led to substantial increases in the expression of CXCL10, CXCL11, and CXCR3 mRNA by urinary bladder leukocytes as well as modest increases in the expression of CXCL9 and CXCR3 transcripts by iliac lymph node lymphocytes than compared to normal, untreated mice." (PMID 18957084, 2008).
dermatitis (2 papers, 2019 to 2022). An inflammatory process affecting the skin. "However, a similar dichotomy in the expression of CXCL9 and CXCL10 (and CXCL11) has been described before for different human skin disorders." (PMID 31447864, 2019).
emphysema (2 papers, 2004 to 2020). "CXCL11, which is secreted by the recruited macrophages, stimulated the activation of Th1/Tc cells and induced chronic inflammation and emphysema; macmoondong decoction significantly suppressed the expression of CXCL11 to similar levels induced by Spiriva treatment." (PMID 32382300, 2020).
epilepsy (2 papers, 2019 to 2024). A brain disorder characterized by episodes of abnormally increased neuronal discharge resulting in transient episodes of sensory or motor neurological dysfunction, or psychic dysfunction. "Our results suggest that the effect of CXCL11 levels in increasing the risk of epilepsy remains valuable after adjusting for the effect of GM on epilepsy." (PMID 39315097, 2024). "Genus Family XIII AD3011 group was positively associated with CXCL11 levels (OR=1.1398, 95%CI =1.0168~ 1.2776, P=0.0247) among the epilepsy-associated GM and inflammatory proteins." (PMID 39315097, 2024). "CXCL11 levels and VEGFA levels increased the risk of epilepsy, CXCL1 levels, CXCL9 levels, IL-6 levels, TRAIL levels, and VEGFA levels were associated with an increased risk of FE and TTNFSF14 levels, VEGFA levels were associated with an increased risk of GE." (PMID 39315097, 2024). "The effect of CXCL11 levels on epilepsy remained significant after adjustment for Genus Family XIII AD3011 group." (PMID 39315097, 2024). "These suggest that CXCL11/CXCR3 may be involved in seizure and provide a rationale for targeting the down-regulation of the CXCL11/CXCR3 axis for the treatment of epilepsy." (PMID 39315097, 2024). "Therefore, we conclude that CXCL11 levels indirectly affect the association between Genus Family XIII AD3011 group and epilepsy." (PMID 39315097, 2024). "Furthermore, we found that CXCL11 mediates the association between Genus Family XIII AD3011 group and epilepsy." (PMID 39315097, 2024). "Furthermore, we found that C-X-C motif chemokine 11 (CXCL11) levels mediated the causal association between Genus Family XIII AD3011 group and epilepsy." (PMID 39315097, 2024). "Two inflammatory proteins, namely, C-X-C motif chemokine 11(CXCL11) levels (OR=1.1078, 95%CI =1.0255~ 1.1967, P=0.0093) and Vascular endothelial growth factor A (VEGFA) levels (OR=1.0721, 95%CI =1.0219~ 1.1247, P=0.0044) were positively associated with epilepsy." (PMID 39315097, 2024). "In contrast, the effect of Genus Family XIII AD3011 group on epilepsy was not significant after adjusting for CXCL11." (PMID 39315097, 2024). "Relatively few studies have examined the relationship between CXCL11/CXCR3 and epilepsy." (PMID 39315097, 2024). "However, the expression patterns of CXCL12, CXCL11, CXCR4, and CXCR7 in epilepsy remain unclear." (PMID 31672961, 2019). "We found no significant changes in CXCR4, CXCL11, and CXCL12 expression levels in the hippocampus of mice with KA-induced epilepsy or in the brain tissues of patients with TLE." (PMID 31672961, 2019).
head and neck cancer (2 papers, 2020 to 2025). A primary or metastatic malignant neoplasm affecting the head and neck. "CXCL11 plays a role in the progression of different cancers, including head and neck cancer and CRC." (PMID 40822974, 2025).
Hepatitis (2 papers, 2015 to 2024). Inflammation of the liver. "Conversely, other ISGs, including ISG20, IFI16, APOBEC3G, CXCL10, and CXCL11, which were predominantly expressed in T cells and nMacs, and upregulated during the hepatitis phase, showed a positive correlation with serum ALT levels, indicating their involvement in liver injury." (PMID 39135698, 2024).
herpes simplex encephalitis (2 papers, 2017 to 2019). Herpes simplex virus encephalitis (HSE) is caused by the infection of the central nervous system by Herpes simplex virus (HSV) that could have a devastating clinical course and a potentially fatal outcome particularly with delay or lack of treatment. "We have previously shown that CXCL11 production distinguishes herpes simplex meningitis from herpes simplex encephalitis." (PMID 30777092, 2019).
inflammatory skin disease (2 papers, 2017). Inflammatory skin disorders covers a broad category that includes many conditions ranging in severity, from mild itching to grave medical health complications These disorders are common in people of all ages and races. "Another previous study reported findings similar to our data, showing differences in the expression of CXCL9, CXCL10, and CXCL11 in different types of inflammatory skin disease, including lichen planus, chronic discoid lupus, and psoriasis." (PMID 28436448, 2017). "Specifically, chemokines CXCL9, CXCL10, and CXCL11 were involved in the T cell recruitment and infiltration in inflammatory skin diseases." (PMID 28427244, 2017).
injury (2 papers, 2019 to 2020). Damage inflicted on the body as the direct or indirect result of an external force, with or without disruption of structural continuity. "The upregulation of MX1 and CXCL11 at mRNA and of STAT1 at the protein level in the HIVgp120tg hippocampus as well as the complete abrogation of the increases in the absence of IFNAR1 confirmed the type I IFN response we previously observed in this model system of HIV-associated brain injury." (PMID 32727588, 2020). "Similarly, we also found that, compared to sham rats, IL-1β, CXCL1, CXCL11, CCL2, and transcription factor (Spil/Pu.1, Runx3, and IκBz) are obviously elevated at 7 days following nerve injury." (PMID 31708740, 2019).
lupus (2 papers, 2010 to 2023). "In this regard, it has been reported that levels of CXCL9, CXCL10 and CXCL11 correlate with lupus disease activity." (PMID 21050432, 2010).
lymph node metastasis (2 papers, 2020 to 2022). "Many studies have indicated that CXCL11 promotes OC progression by mediating angiogenesis, lymph node metastasis, and immune infiltration." (PMID 35227296, 2022). "CXCL11 showed significant negative correlation with lymph node metastasis and distant metastasis." (PMID 33049716, 2020).
Mycobacterium infection (2 papers, 2016 to 2017). Infections with bacteria of the genus Mycobacterium. "As was reported, pathogen specific Th17 cells generated during mycobacterium infection induce the expression of CXCL9, CXCL10 and CXCL11, as well as IL-17 produced dictate the migration of other important effectors cell types to control the infection." (PMID 29259310, 2017).
myositis (2 papers, 2022 to 2025). "Previous studies have also shown elevated muscle levels of numerous cytokines associated with type 1 inflammation, including CCL5, CXCL9, CXCL10, CXCL11, IFNG, and TNF in IBM patients compared to various myositis and non-myositis controls." (PMID 40034760, 2025).
neuroblastoma (2 papers, 2022 to 2025). Neuroblastoma (NB) is the most common solid, extracranial childhood tumor. "Using neuroblastoma as a model, CancerPAM analysis of tumour sequencing data identifies optimal knock-in sites for pro-inflammatory cytokines (CXCL10, CXCL11, IFNG), and CancerPAM rankings correlate strongly with target-site specificity and knock-in efficiency, validating its predictive performance." (PMID 41366257, 2025).
neuroborreliosis (2 papers, 2017 to 2022). "CXCL11 expression is not unique for HSM as it has been observed in neuroborreliosis and enteroviral meningitis." (PMID 28693588, 2017).
non-alcoholic fatty liver disease (2 papers, 2021). "Moreover, a recent systematic review and meta-analysis suggested that the chemokines, CCL3, CCL4, CCL5, CCL20, CXCL8 and CXCL11, are implicated in the pathogenesis of non-alcoholic fatty liver disease, post-traumatic stress disorder, and also different types of cancers." (PMID 35242125, 2021). "Moreover, a recent systematic review and meta-analysis suggested that chemokines, CCL3, CCL4, CCL5, CCL20, CXCL8 and CXCL11, are implicated in the pathogenesis of non-alcoholic fatty liver disease, post-traumatic stress disorder, and also different types of cancers." (PMID 34054797, 2021).
osteoarthritis (2 papers, 2019 to 2025). A noninflammatory degenerative joint disease occurring chiefly in older persons, characterized by degeneration of the articular cartilage, hypertrophy of bone at the margins and changes in the synovial membrane. "In osteoarthritis (OA), CXCL8 and CXCL11 affect chondrocyte apoptosis and proliferation through the JAK-STAT and NF-κB signaling pathways." (PMID 41416066, 2025).
ovarian tumor (2 papers, 2018 to 2019). "As for CXCR7, CXCL11 was also significantly elevated in ovarian tumor stroma compared with normal sections, while stromal CXCR3 expression was not, emphasizing a selective contribution of the CXCR7/CXCL11 axis." (PMID 30051594, 2018). "Consistent with such positive relation, CXCR7 expression was significantly correlated with that of CXCL11 in the mesenchymal subtype of ovarian tumors." (PMID 30051594, 2018). "This is also consistent with the increased expression of CXCR7 and the strong correlation with CXCL11 preferably taking place in the mesenchymal subtype of ovarian tumors, providing an activation pathway for EM transition." (PMID 30051594, 2018). "To further validate their possible contribution to OC mesenchymal subtype, we found that both CXCR7 and CXCL11 strongly correlate with genes associated with ECM and OC invasion, such as PRRX1, TMEM45A, and CTSK, when analyzed in the mesenchymal counterpart of ovarian tumors." (PMID 30051594, 2018). "Lastly, we show that the combination of high mRNA expression levels for three IFN-γ target genes (CXCL10, CXCL11 and IFI16) correlated with overall survival in ovarian tumors from the TCGA database, pointing to the potential clinical significance of this pathway in HGSOC." (PMID 31840082, 2019).